VDR (vitamin D receptor)
Diseases named in the same sentence as VDR in open-access papers (continued):
Sharing a sentence is not in itself a finding about the gene and the disease.
cardiovascular disease (55 papers, 2011 to 2025). "Network construction using proteins in these clusters and retrieval of 10,000 publications with statistically significant protein network overlaps identified cardiovascular disease-associated functions regulated by the nuclear vitamin D receptor." (PMID 38984353, 2024). "VDR Bsm I gene polymorphism may predict cardiovascular disease risk of MDH patients, and provided theoretical basis for early detection and prevention of cardiovascular complications." (PMID 35033017, 2022). "The VDR gene polymorphisms have been evaluated as independent risk factors in various diseases such as prostate cancer, inflammatory bowel disease, osteopenia and tuberculosis, Parkinson's disease, diabetes and cardiovascular diseases." (PMID 33863283, 2021). "Reduced vitamin D receptor signaling might be a potential mechanism underlying increased foam cell formation, resulting in an accelerated development of cardiovascular disease in diabetic subjects." (PMID 29966312, 2018). "Underlying biological mechanisms, by which the VDR genetic polymorphisms may modify the effect of lead on cardiovascular disease, are not well understood." (PMID 25582168, 2015). "According to recent clinical and experimental studies, VDR may indeed play a role in cardiovascular diseases and the VDR gene polymorphism could have an important role in transactivation efficiency of target genes." (PMID 24729966, 2014). "Interestingly, certain bacterially modified bile acids (3-oxo-staphylococcal acid and staphylococcal acid) can also activate the vitamin D receptor (VDR), and genetic studies in both humans and mice have shown that VDR activation is associated with cardiovascular disease." (PMID 36439791, 2022). "The evident link between astragaloside and the modulation of VDR signaling strengthens the case for the viability of VDR as a potential target for cardiovascular disease treatment." (PMID 38318147, 2024). "Due to the potential of T2 to induce 1,25(OH)2D degradation, activate VDR, and increase FGF23, which is associated with cardiovascular diseases, the safety of UV-B-treated foods is questionable." (PMID 35958252, 2022). "It is reported that active metabolites of vitamin D bind to the VDR, which regulates the genes in essential processes and has a role in pathways of cardiovascular diseases, including inflammation, thrombosis, and the renin-angiotensin system." (PMID 33923622, 2021). "Strong support for the involvement of vitamin D in the pathogenesis of cardiovascular diseases comes from VDR knockout mice (VDR−/−)." (PMID 32911795, 2020). "Vitamin D is associated with cardiovascular health through activating the vitamin D receptor that targets genes related to cardiovascular disease (CVD)." (PMID 32235811, 2020). "Although, there is no clear information on the relationship between serum 25-OH-vitD and life expectancy, experimental studies have shown that vitamin D receptor-knockout mice develop metabolic defects and cardiovascular disorders." (PMID 31699030, 2019). "Thus, VDR rs11574077 represents an intronic variant of unknown functional significance, although it was reported to impact the risk of developing some tumors and cardiovascular disease." (PMID 29706892, 2018). "Athero-susceptible DMRs were also associated with genes of the matrix metalloproteinase pathway and vitamin D receptor activation pathway, both of which have been shown to play critical roles in cardiovascular disease." (PMID 26148682, 2015). "The association between vitamin D receptor (VDR) polymorphism and the risk of cardiovascular diseases (CVD) remains unclear." (PMID 34578994, 2021). "VDR’s ubiquitous presence in tissues points to the additional roles of vitamin D in the body, including its role in immunity and pathological conditions such as cancer and cardiovascular diseases." (PMID 33863283, 2021).
cardiovascular disease (continued). "Vitamin D receptor activators (VDRA) may exert pleiotropic effects on cardiovascular disease, malignancy, and infections among dialysis patients, but recent studies have mainly focused on cardiovascular outcomes." (PMID 28139665, 2017). "Furthermore, the Fok-I and Apa-I VDR polymorphisms were not related to anthropometric and metabolic risk factors for cardiovascular disease." (PMID 37375641, 2023). "Subsequent clinical trials on VDR have revealed that VitD supplementation does not reduce mortality related to tumors or cardiovascular diseases." (PMID 38600588, 2024). "Interestingly, VDR knockout mice develop a premature aging phenotype similar to HGPS patients, with early alopecia, growth retardation, muscle atrophy, cardiovascular disease, and reduced lifespan." (PMID 27145372, 2016). "The precise mechanism of how the ligand/VDR complex may help protect individuals against cardiovascular diseases is not clear." (PMID 24729966, 2014).
metabolic disorders (40 papers, 2008 to 2026). "The aim of this study was to assess the differentiation by the VDR genotype of the risk factors for so-called chronic low-grade inflammation and metabolic disorders." (PMID 37375641, 2023). "Low levels of vitamin D or inactivating polymorphisms in VDR have been associated with inflammatory and metabolic disorders." (PMID 30828578, 2018). "Future studies are required to clarify the causal relationship between VDR gene polymorphism, low vitamin D status and metabolic disorders including developing T2DM." (PMID 30166978, 2018). "The aim of the present study was to assess the relationships between VDR polymorphisms (ApaI, BsmI, FokI, and TaqI) and selected cytokines, inflammatory factors, and metabolic parameters in relation to the risk of metabolic disorders and atherogenicity in Polish postmenopausal women." (PMID 37375641, 2023). "Thus, it can be concluded that both, diet and VDR status, play a role in metabolic diseases, inflammation, risk of colon cancer, and epigenetic pathways." (PMID 33396382, 2020). "In the current study, we hypothesize that host factors (e.g., VDR status in specific tissues) modulate microbial metabolites and the microbiome, thus contributing to the high risk of metabolic diseases." (PMID 32355205, 2020). "VDR is expressed in adipose tissues and Vit-D regulates adipogenesis and the metabolic and endocrine function of these tissues, which may contribute to the high risk of metabolic diseases in Vit-D insufficiency." (PMID 38732596, 2024). "However, despite the asserted beneficial effect of VDR signaling on the cardiovascular system, other epidemiological studies, mainly priming VDR signaling via vitamin D supplementation, suggest a disease-causal role for VDR in the pathogenesis of cardiovascular and metabolic diseases." (PMID 38318147, 2024). "More SNPs are expected to be identified in future because of the large size of the VDR gene and a number of those already described have been found to be associated with some chronic diseases, including multiple sclerosis, rheumatoid arthritis, and some autoimmune and metabolic diseases." (PMID 37189820, 2023). "VDR gene FokI SNPs may be considered as a risk factor for metabolic disorders in GDM." (PMID 31096931, 2019). "Understanding how metabolic disorders and systemic diseases affect VDR expression and signaling in hair follicles remains crucial for developing more effective treatments for patients with complex medical conditions." (PMID 41473843, 2026). "Recent evidence has demonstrated that various metabolic disorders can significantly alter VDR expression patterns in multiple tissues." (PMID 41473843, 2026). "Emerging evidence positions vitamin D as a therapeutic modulator in metabolic disorders, particularly through VDR-mediated anti-inflammatory actions in hepatic and extrahepatic tissues." (PMID 40564179, 2025). "The vitamin D receptor (VDR), best known for its role in calcium and phosphate regulation, also impacts immune function and metabolic diseases, influencing insulin sensitivity and inflammatory responses." (PMID 40926269, 2025). "In human studies, clinical evidence also supports a link between the VD/VDR axis and metabolic diseases, although findings remain inconsistent across populations." (PMID 41226298, 2025). "New insights into the regulation of vitamin D–related enzymes and the differential mechanism of action of VDR have demonstrated potential links between several metabolic disorders and vitamin D effects." (PMID 38676447, 2024). "In summary, new insights into the regulation of vitamin D–related enzymes and the differential mechanism of action of VDR have demonstrated important links between metabolic disorders and vitamin D metabolism." (PMID 38676447, 2024).
metabolic disorders (continued). "A recent preliminary study assessed the relationship between the VDR genotypes, plasma concentrations of vitamin D metabolites, and the occurrence of cardiovascular and metabolic disorders in 58 Polish patients treated for various cardiological diseases." (PMID 37189820, 2023). "The VDR gene has been confirmed to be significantly involved in the regulation of the endocrine system, suggesting that it is a potential candidate gene for metabolic disorders." (PMID 35526059, 2022). "This study aimed to assess a relationship between the VDR genotypes, plasma concentrations of vitamin D metabolites, and the occurrence of cardiovascular and metabolic disorders." (PMID 34578994, 2021). "Studies suggest that VD/VDR signaling influences key processes such as adipogenesis, inflammation, and mitochondrial function, positioning this axis as a potential therapeutic target for mitigating metabolic disease." (PMID 41226298, 2025). "Hence, research is needed to examine the role of VDR and VDBP genetic variants and possibly their mutations in OSA severity and OSA‐related metabolic disorders." (PMID 36746181, 2024). "Recent research has suggested that VDR also plays an essential role in metabolic diseases." (PMID 37432296, 2023). "Furthermore, with a similar intensity to the GC gene, the gene VDR seemed to be involved in nutritional and metabolic diseases." (PMID 36430729, 2022). "Our study highlights the gender differences, tissue specificity, and potential gut-liver-microbiome axis mediated by VDR that might trigger downstream metabolic disorders." (PMID 32355205, 2020). "The results indicated perilla oil rich in ALA can regulate the expression of multiple nuclear transcription factors, including VDR, thus alleviating liver cholesterol overload and metabolic disorders, and perilla oil can be a potential dietary therapeutic tool against NAFLD." (PMID 27642591, 2016). "Further functional studies of VDR and MEGALIN gene in relation to cardiometabolic risk can provide important validation for our results and can contribute to our understanding of how vitamin D metabolism-related genes can influence metabolic disorders in various populations." (PMID 29795187, 2018). "Vitamin D derivatives with selective modulatory activity on the vitamin D receptor (VDR) have been developed for the treatment of VDR-related diseases, including bone and calcium diseases, malignancies, immune and inflammatory diseases, and metabolic disease." (PMID 37509118, 2023). "Thus, the results of this study reveal critical roles of a vitamin D/VDR axis in optimal expression of defensins and tight junction genes in support of intestinal integrity and eubiosis to suppress NAFLD and metabolic disorders." (PMID 27895587, 2016). "However, we did not study the effect association of BMI with metabolic disorders and alterations in VDBP, VDR, and VD." (PMID 38586664, 2024). "Indeed, we demonstrated the existence of an independent relationship between VDR and ANGPTL4 expression in human VAT, regardless of potential confounders such as age, sex, body adiposity, and metabolic disease." (PMID 33003532, 2020).
renal disease (31 papers, 2012 to 2025). "The VDR TaqI C-allele, under allele contrast fixed effect model, was associated with renal diseases calculated collectively for DN, ESRD and NL (OR: 1.11, 95% CI: 1.03–1.20, p = 0.008)." (PMID 31822280, 2019). "Considering the pivotal role of VDR in maintaining normal renal function, a number of studies have explored the possibility of association of VDR gene polymorphisms with renal disease risk." (PMID 31822280, 2019). "Among the different ethnic groups, Turkish population showed strong association between VDR TaqI polymorphism and renal disease in allele contrast model (C vs. T, OR: 1.19, 95% CI: 1.01–1.42, p = 0.04)." (PMID 31822280, 2019). "The TaqI (rs731236) and ApaI (rs7975232) polymorphisms of VDR gene are widely studied for their association with renal disease risk." (PMID 31822280, 2019). "The present meta-analysis identifies TaqI and ApaI polymorphisms of VDR gene as risk factors for renal diseases." (PMID 31822280, 2019). "Ethnicity, sample size, gene-environmental interactions appear to be responsible for inconsistencies observed in the association studies examining VDR polymorphisms and renal diseases." (PMID 31822280, 2019). "Accordingly, a number of studies have investigated the effects of polymorphisms in VDR gene on renal disease etiology." (PMID 31822280, 2019). "The fixed effect model showed positive association of VDR ApaI polymorphism with all the renal disease cases (C vs. A, OR: 1.10, 95% CI: 1.01–1.19), whereas, random effect model showed null association (OR: 1.05, 95% CI: 0.93–1.19)." (PMID 31822280, 2019). "In our study, SLE patients with the F/F and F/f genotypes of the FokI VDR polymorphism exhibited a significantly increased risk of developing renal disease." (PMID 23065277, 2013). "The deficiency of 25OHD or VDR is reported to activate renin-angiotensin system resulting in high angiotensin II levels, which damage renal parenchyma leading to increased risk for renal disease." (PMID 31822280, 2019). "Increasing data show that vitamin D receptor agonists (VDRAs) exert beneficial effects in renal disease and possess anti-inflammatory properties, but the underlying mechanism remains unknown." (PMID 26064952, 2015). "Moreover, VDR gene polymorphisms have been shown to be associated with left ventricle hypertrophy in patients with renal diseases." (PMID 26451144, 2015). "However, genotyping for VDR variants might help to improve the management of renal diseases given that VDR genotypes have been shown to influence the response to therapy." (PMID 24618509, 2014). "The accumulating evidence highlights a significant yet complex relationship between VDR and kidney diseases." (PMID 38318147, 2024). "Previous results from clinical and animal studies have suggested that VDR activation has beneficial effects on various renal diseases." (PMID 36555517, 2022). "VDR agonists can inhibit NF-κB activity and reduce renal podocyte inflammation in some experimental renal disease models (e.g., azithromycin-induced renal injury), thereby alleviating renal injury." (PMID 35765066, 2022). "The protective effect of vitamin D/VDR in kidney diseases has been validated by a lot of research works including ours." (PMID 31996668, 2020). "It is now well recognized that VD/VDR plays an important role not only in regulating blood calcium and phosphorus levels but also in the progression of many other diseases such as kidney diseases, especially in DN." (PMID 32766307, 2020). "The deficiency of vitamin D receptor (VDR) or its ligand, vitamin D3, is linked to the development of renal diseases." (PMID 31822280, 2019). "Another vitamin D receptor agonist, doxercalciferol, decreased inflammation and oxidative stress in a dietary fat-induced renal disease mouse model." (PMID 27429711, 2016). "Our findings are also consistent with some evidence for a beneficial effect of VDR signalling in the prevention of arterial medial calcification (as occurs in kidney disease)." (PMID 24586387, 2014).
renal disease (continued). "Numerous studies indicate the involvement of vitamin D/VDR in diverse renal diseases." (PMID 40620673, 2025). "Moreover, the genetic landscape of VDR in kidney diseases has been illuminated by a comprehensive meta-analysis." (PMID 38318147, 2024). "In addition, studies have demonstrated that Vitamin D could activate the Nrf2-Keap1 antioxidant pathway and improve renal disease in diabetic rats; it can also activate the Nrf2 signaling pathway via vitamin D receptor to ameliorate leptin-induced oxidative stress." (PMID 32184720, 2020). "Paricalcitol (25-dihydroxyvitamin D2), a vitamin D receptor (VDR) activator, is reported to improve cardiovascular health or survival in patients with advanced kidney disease who tend to have low vitamin D." (PMID 32235811, 2020). "In terms of renal disease, HIV induces podocyte injury via downregulation of the vitamin D receptor (VDR), which is attributable to epigenetic effects of the virus on the VDR promoter [46••]." (PMID 32880756, 2020). "Moreover, impaired 25-hydroxylation and 1α-hydroxylation by liver or renal disease, as well as genetic causes or mutated nonfunctioning VDR, might explain these gender differences." (PMID 31635199, 2019). "Among the potential explanations for this discrepancy, we should now add the lack of MXRA5 in rats and mice used as models of kidney disease, while this potentially nephroprotective molecule is present in humans and down‐regulated by VDR activators." (PMID 27599751, 2017). "However, the frequency of the VDR F/F and F/f genotypes of FokI was statistically different between patients with renal disease and patients without this symptom OR = 3.228 (1.534–6.792, p = 0.0014), pcorr = 0.0476)]." (PMID 23065277, 2013).